ACP7 (acid phosphatase 7, tartrate resistant (putative))
Description:
Putative metallophosphoesterase belonging to the purple acid phosphatase family that catalyzes the hydrolysis of phosphate esters to alcohol and phosphate under acidic conditions.
Synonyms: PAPL; PAPL1; FLJ16165
Tractability: Antibody: UniProt places it where antibodies can reach, with high confidence; UniProt predicts a signal peptide or a membrane-spanning region; its Gene Ontology location is reachable by antibodies, with medium confidence.
Gene: Protein-coding gene on chromosome 19 (39,083,913 to 39,111,497, forward strand). Ensembl gene ENSG00000183760.
Subcellular location: Secreted
Gene Ontology:
Molecular function: acid phosphatase activity; hydrolase activity; metal ion binding
Cellular component: extracellular region
Genetic constraint (gnomAD): Loss-of-function variants: 58 observed, 62.94 expected, observed/expected ratio (o/e) 0.92, 90% interval 0.75 to 1.15. The upper end of that interval is the gene's LOEUF score, 1.15, which puts it in group 5 of 6, group 1 being the genes least tolerant of losing a copy. Missense variants: 574 observed, 616.71 expected, observed/expected ratio (o/e) 0.93, 90% interval 0.87 to 1. Synonymous variants: 237 observed, 243.83 expected, observed/expected ratio (o/e) 0.97, 90% interval 0.87 to 1.08.
Homologues: Orthologues: chimpanzee ACP7 (99% identical), macaque ACP7 (99% identical), pig ACP7 (92% identical), dog ACP7 (91% identical), rat Acp7 (88% identical), guinea pig ACP7 (87% identical), rabbit ACP7 (87% identical), mouse Acp7 (86% identical), tropical clawed frog acp7 (61% identical), zebrafish acp7 (55% identical), Drosophila melanogaster CG1637 (52% identical), Caenorhabditis elegans F21A3.11 (48% identical).
Diseases named in the same sentence as ACP7 in open-access papers:
ACP7 is named in the same sentence as 9 diseases in open-access papers, as found by Europe PMC text mining. Sharing a sentence is not in itself a finding about the gene and the disease. The quoted sentences say what the papers report.
glioblastoma (2 papers, 2023). The most malignant astrocytic tumor (WHO grade IV). "ACP7 is an acid phosphatase with marked relative expression in fibroids in all groups but more so in Blacks; the physiologic function of this gene is unexplored, except in one study showing an association with glioblastoma survival." (PMID 37686244, 2023). "While the listed genes have been previously reported to be related to glioblastoma or other types of cancer, ACP7 was identified as a novel gene related to the prognosis of GBM." (PMID 36836422, 2023).
glioma (1 paper, 2023). A benign or malignant brain and spinal cord tumor that arises from glial cells (astrocytes, oligodendrocytes, ependymal cells). "Inflammatory microglial cells, dendritic cells, myeloid cells, and glioma stem cells were highly expressed in GBM tissue, and ACP7, EPPK1, PCDHA8, RHOD, DRC1, ZIC3, and PRLR were significantly associated with survival." (PMID 36836422, 2023).
head and neck cancer (1 paper, 2023). A primary or metastatic malignant neoplasm affecting the head and neck. "Lastly, ACP7, acid phosphatase 7, has not been previously reported to play a role in tumorigenesis or TMZ resistance, but according to the Human Protein Atlas, ACP7 is highly expressed in head and neck cancer and lung cancer." (PMID 36836422, 2023).
tumor (1 paper, 2023). "The expression of several race-associated genes was also dependent on the MED12 mutation status of the tumor, being higher (FRAT2, TNFRSF19, ACP7, IRS4, PLEKHG4B, KRT17, SLN, and ZNF703) or lower (CAV2) in the mutated specimens compared with wild-type tumors." (PMID 37686244, 2023).
ACP7 also shares sentences with these, for which no sentence is quoted: cancer (2 papers); infection (2); leiomyoma (1); lung carcinoma (1); melanoma (1).